CCL5 (C-C motif chemokine ligand 5)
Diseases named in the same sentence as CCL5 in open-access papers (continued):
Sharing a sentence is not in itself a finding about the gene and the disease.
tumor (continued). "Furthermore, we observed that fibroblasts that were exposed to tumor cell-conditioned media for 4 h produced significantly more CCL5 protein than fibroblasts exposed to tumor cell factors for 2 h, suggesting that the magnitude of the fibroblast CCL5 protein production is dose-dependent." (PMID 33868996, 2021). "Finally, the CCL2 from tumor cells and CCL5 from activated endothelial cells can further recruit the inflammatory monocytes/macrophages to prepare the cellular assembly of CTCs, platelets, neutrophils, endothelial cells and monocytes/macrophages required for efficient extravasation of CTCs." (PMID 33414786, 2020). "In CCR5-deficient mice, decreased CCL5 levels were observed and anti-tumour effects were absent." (PMID 32098198, 2020). "However, the authors suggested that the main sources of circulatory and tissue CCL5 were likely activated macrophages and T cells, which may contribute to the tumor expansion." (PMID 32545571, 2020). "Mice inoculated with Pan02-pLV-FOXP3 cells were treated with PD-L1 and/or CCL-5 blocking antibodies (200 μg, intraperitoneal injection q3d) for 3 weeks, and when the tumor volumes reached approximately 70 mm3, the effects of single or combined treatment on tumor growth were evaluated." (PMID 32300119, 2020). "Interestingly, several other cytokines reported to be associated with senescence maintenance and tumor-suppression, such as IL1α, IL1β, TGF-β, and CCL5, exhibited upregulated expression in the LY2835219 monotherapy group but did not exhibit downregulated expression in the combination group." (PMID 33116117, 2020). "Indeed, in vitro treatment with CCL2 and CCL5 stimulated neutrophils to kill tumor cells." (PMID 33105656, 2020). "Indeed, in the mouse PDX (patient-derived xenografts) model of human malignant phyllodes tumor, intraperitoneal injection of maraviroc, CCR5 inhibitor, or CCL5 neutralizing antibody prevents the recruitment of monocytes to tumors and dramatically suppress tumor growth." (PMID 33224886, 2020). "In light of the patient survival curves stratified by CD8 and CCL5 tumor expression, these T cell–microglia interactions may be particularly relevant to LGGs, where MDK/CCL4-independent mechanisms involving CD8+ T cells and microglia result in CCL5 support of tumor growth." (PMID 32358581, 2020). "Inflammatory CC (CCL2, CCL3, CCL5) and CXC (CXCL1, CXCL2, CXCL5, CXCL6, and CXCL8) chemokines recruit at the tumor site CCR2+ monocytes and CXCR2+ neutrophils that differentiate into tumor associated macrophages (TAMs) and tumor associated neutrophils (TANs), exerting pro- or anti-tumoral role." (PMID 30894861, 2019). "Higher CCL5 may be involved in developing tumor tolerance resulting in the poor TNBC prognosis." (PMID 30850664, 2019). "Therefore, by targeting autophagy through Becn1 and CCL5, NK cell filtration to the tumor could increase and prevent tumor immune escape." (PMID 31396523, 2019). "In addition, the expression of CCL5 on TAMs is followed by the therapy of tumor." (PMID 31629410, 2019). "CCL5 secreted by endothelial cells may act as the driver of tumor metastasis." (PMID 30200999, 2018). "To explore the possibility of intrinsic CCL5-deficiency in CD8+ T cells to affect the migration and antitumor activity of CD8+ T cells, we adoptively transferred CCL5+/+ CD8+ T cells or CCL5−/− CD8+ T cells isolated from tumor-bearing mice into CCL5−/− mice or CCL5+/+ mice, respectively." (PMID 29991744, 2018). "Moreover, tumor cells, upon CCL5 stimulation, can produce VEGF or, by secreting CCL5, may recruit CCR5-expressing TAMs." (PMID 29772686, 2018). "Thus, naturally occurring Foxp3+ T-regs may be induced to migrate from the peripheral blood to the tumor sites by the chemokines CCL17, CCL22, and CCL5 and then increase in number by tumor-related factors to create a favorable environment for tumor growth." (PMID 29772686, 2018).
tumor (continued). "More recently, a retrospective analysis of 105 patients with GC demonstrated that increased CCL5 serum levels correlated with more advanced T and N stages, poorly- or undifferentiated histological types, peritoneal metastasis, higher rates of residual tumor, and shorter survival." (PMID 29772686, 2018). "In addition, CCL5 production by tumors enhances the infiltration of tumor-associated macrophages (TAM) and myeloid derived suppressor cells (MDSCs), leading to the production of growth factors that enhance tumor cell proliferation." (PMID 29216863, 2017). "Indeed, the MDA-MB-231.CCR5−/− cells are more sensitive to inhibitors blocking glucose uptake and glutamine catabolism and have a lower proliferation rate than MDA-MB-231.CCR5+/+ cells, in further support of a role for CCL5 activation of CCR5 contributing to tumor cell metabolism." (PMID 29216863, 2017). "Thus, by secreting remarkable amounts of CCL2 and CCL5, ADSCs that have been recruited into the tumor stroma could promote tumor progression by further increasing the number of TAMs in the tumor microenvironment." (PMID 28545495, 2017). "Having shown that T cell chemotaxis is facilitated by CCL5 regulating glucose uptake, we speculated that CCL5 may enhance tumour cell proliferation, invasion and metastasis by a similar mechanism, because cancer cells exhibit significant dependence on glucose for their growth and survival." (PMID 27335323, 2016). "Importantly, inhibition of CCL5 production by cancer cell or by the tumor microenvironment may represent an additional strategy to block cancer progression." (PMID 27166194, 2016). "Therefore, it is likely that radiation not only induces activation of the STING pathways to activate the Th1/Tc1 T cells but also up-regulates NF-κB to activate CCL2 and CCL5 to attract the activated Th1/Tc1 cells infiltration into the tumor microenvironment to suppress tumor development." (PMID 27014915, 2016). "Thus, in vivo suppression of cancer cell CCL5 led to diminished tumor growth and vascular effects." (PMID 27863423, 2016). "Since CCL5 could act locally promoting cell movement, it could be involved in cancer invasion of the surrounding adipose tissue, which is one of the biologic indicators of tumor aggressiveness." (PMID 27027351, 2016). "Herein, we investigated whether CCL5 promoted tumor lymphangiogenesis in vivo." (PMID 27166194, 2016). "However, the neutralizing antibodies for CCL5 or CXCL10 significantly hampered the migration induced by tumor supernatant (pCCL5 < 0.05; pCXCL10 < 0.01), and the migration of T lymphocytes was further inhibited by the combined use of anti-CCL5 and anti-CXCL10 neutralizing antibodies (p < 0.001)." (PMID 26317795, 2015). "Furthermore, counteracting the infiltration of TAM by antagonizing the key chemokine mediator of macrophage recruitment i.e. CCL5 markedly reduced tumor infiltrate and reduced tumor growth, thereby emphasizing the importance of recruitment of TAMs during tumor progression." (PMID 25051364, 2014). "CXCL8 may also contribute to tumor growth, while CCL5 may induce anti-tumor responses." (PMID 25201625, 2014). "We then investigated whether CCL5 could promote tumor angiogenesis in vivo." (PMID 25301739, 2014). "CCL5/CCR5 interactions may favor tumor development in multiple ways: acting as growth factors, stimulating angiogenesis, modulating the extracellular matrix, inducing the recruitment of additional stromal and inflammatory cells, and taking part in immune evasion mechanisms." (PMID 24523569, 2014). "Additionally, RANTES/CCL5 has been shown to promote tumor proliferation, invasion, metastases and angiogenesis, which may also contribute to the development of PEL and KS." (PMID 22624040, 2012).
tumor (continued). "In addition to their ability to promote the release of CCL2 and CCL5 by the tumor cells, it is possible that TNFα and IL-1β act directly to elevate processes that are required for local recurrence or metastasis formation, which identify the IDC-with-relapse group of patients." (PMID 21486440, 2011). "Tumor-associated macrophages (TAM) derive mostly from circulating monocytes which are attracted into tumor sites, by locally produced chemotactic factors, such as CCL2, CCL5, CCL7, CCL8, CXCL12, vascular endothelial growth factor (VEGF), and macrophage colony stimulating factor (M-CSF)." (PMID 24212934, 2011). "(c) Signaling molecules also play a role, as the density of tumor-infiltrating T cells is negatively associated with expression of VEGF, B7-H1/PD-L1 and endothelin B receptor by tumors and positively associated with expression of the chemokines CXCL9, CCL21, CCL22, CCL2 and CCL5." (PMID 19641607, 2009). "This review compiles current knowledge on the significance of lesser-known chemokines in MM tumor processes, including CXCL13, CCR2 ligands (CCL2 [MCP-1], CCL7 [MCP-3]), CCL4, CCL5 (RANTES), CCL17, CCL20, CCL27, CCL28, and CX3CL1 (fractalkine)." (PMID 41749925, 2026). "Accumulating evidence indicates that inflammatory mediators-including CCL2, CCL3, CCL5, CXCL1, CCL20, TNF-α, IL-6, IL-8, and TGF-β-contribute to tumor growth, metastasis, immune modulation, and therapeutic resistance." (PMID 42245673, 2026). "Consistent with our Visium analysis, Xenium gene expression analysis revealed that Tfh-like cells located near tumor regions were enriched for C06b CD103+ Tfh-like signature genes, including CCL5, CCL4, GZMA, HAVCR2, and CSF1." (PMID 41542042, 2026). "The attraction of MCs to a tumor requires the action of different chemokines produced by the tumor cells such as the stem cell factor (SCF), CXCL2, CCL2, CCL5, CCL11, CXCL12, CCL15, IL-3, and IL-33." (PMID 41465542, 2025). "By constructing TNBC model in mice, we observed that EA not only inhibited tumor growth but also increased the presence of intratumoral CD8+ T cells and CCL5." (PMID 40475010, 2025). "The results revealed that CCL5 and CCL3 were positively correlated with tumor infiltrating CD8+ T cells in BC." (PMID 41029711, 2025). "The increase in T cells in the TME after aCD40 treatment was possibly due to the increase in the production of chemokines such as CCL5, CCL21, CXCL9, and CXCL10 within the tumor." (PMID 40585246, 2025). "Our findings provide new insights into the CCL5/CCR5 paracrine axis in NEPC, identifying it as an essential mediator of stromal-tumor communication via the PI3K/AKT pathway." (PMID 41152972, 2025). "M-MDSCs, along with monocytes, are predominantly drawn to the tumor by chemokines secreted by the tumor cells, including CCL2, CCL5, and CSF1." (PMID 40722739, 2025). "Overall, LMO7 in tumor cells promotes the differentiation and chemotaxis of Treg cells through TGF-β and facilitates the chemotaxis of Treg cells through CCL5." (PMID 39143228, 2025). "Upon being recruited to inflammatory tumor tissues in response to chemokines like CCL2, CCL5, CXCL8, and CXCL12, MDSCs rapidly produce immunosuppressive mediators, including ARG1, NO, TGF-β, and IL-10, which further impair anti-tumor immunity." (PMID 40563367, 2025). "Concurrently, we observed marked upregulation of multiple pro-tumor factors, including MMP-11, IL-6, IL-1β, CCL5, and CCL2." (PMID 41276817, 2025). "Altogether, these findings suggest that ENH stimulates CCL5 expression by inducing YAP nuclear translocation, which promotes TAMs infiltration, angiogenesis, and tumor progression." (PMID 40536254, 2025). "CCL5 dramatically increased the IC50 value by approximately 2-fold in both human and mouse tumor cells." (PMID 41152972, 2025). "This upregulates the Meox1-Cxcr6/Ccl5 axis, enhances CD8+ T cell infiltration in tumours, and sensitises MSS-CRC to combined radiotherapy and immunotherapy." (PMID 40715695, 2025).
tumor (continued). "First, CAFs directly promote tumour proliferation and metastasis by secreting growth factors (e.g., CXCL11, CCL5): CAF-derived CCL5 enhances HCC metastasis by triggering the HIF1α/ZEB1 axis, while CXCL11 directly promotes HCC cell proliferation." (PMID 40495147, 2025). "These engineered cells exhibited enhanced recognition of PD-L1-positive tumor cells and remodeled the tumor microenvironment (TME) through activation of the CCR5/CCL5 chemokine axis." (PMID 40979124, 2025). "CAAs are better equipped to support tumor invasion and metastasis by releasing CCL2, CCL5, CXCL8, IL-6, leptin, adiponectin, and VEGF." (PMID 40076892, 2025). "Secreted CCL5 binds to CCR5 on tumor cells, activating the PI3K/AKT pathway to potential DNA repair, hence protecting tumor cells from cisplatin-induced cell death." (PMID 41152972, 2025). "Regarding sensory fibers, it has been observed that their stimulation by melanoma tumor cells induces the expression of proinflammatory cytokines, such as CCL2, CCL3, CCL5, which speed up MDSC recruitment and tumor growth." (PMID 41306965, 2025). "In SCLC, combining PARP inhibition with radiotherapy elevates the levels of chemokines such as CCL5 and CXCL10, effectively turning an “immune desert” tumor into an “immune-enriched” tumor that is more receptive to PD-1/PD-L1 blockade." (PMID 41194225, 2025). "Tumor fibrosis, characterized by excessive extracellular matrix deposition, is driven by chemokines such as CCL2 and CCL5, which attract fibroblasts to the TME." (PMID 40134607, 2025). "Further analysis showed increased production of proinflammatory interleukins such as IL‐1β and IL‐16 and accumulation of various chemotactic agents, including CCL3, CCL4, CCL5, CXCL9, CXCL10, and CXCL11, in the tumor tissue." (PMID 41221154, 2025). "Simultaneously, chemokines such as CXCL9, CXCL10, and CCL5 regulate T-cell recruitment, whereas LFA-1 and adhesion molecules like ICAM-1 govern their infiltration and retention within the tumour." (PMID 40361472, 2025). "In parallel, CC chemokine ligand 2 (CCL2) drives monocyte chemotaxis via CCR2 signaling, while CCL5 contributes to TAM aggregation and enhances tumor invasion." (PMID 41142826, 2025). "For example, CAR-T cells expressing CXCR2 or CCR5 have demonstrated improved migration toward tumours that produce CXCL1, CXCL8, or CCL5." (PMID 40624498, 2025). "Our proteomic analysis, based on data from the Clinical Proteomic Tumor Analysis Consortium (CPTAC), focused on CCL5, IL18, and FCER1G." (PMID 41155216, 2025). "Consistently, mRNA expression analysis of subcutaneous tumor tissues derived from CT26 cell injections showed analogous upregulation of PD-L1, CCL5, CXCL9, and CXCL10." (PMID 40959109, 2025). "Recently, it was shown that the protease DPP4 reduces the infiltration of lymphocytes by cleaving and inactivating CCL5 and CXCL10 and that the inhibition of DPP4 improves tumour control and synergises with immune checkpoint therapies (ICBs)." (PMID 40579444, 2025). "The upregulation of chemokine genes Ccl3, Ccl5, Cxcl9, and Cxcl10 suggests that these activated CD8+ T cells possess increased migratory capacity, allowing them to infiltrate the tumor microenvironment more effectively." (PMID 40534857, 2025). "Polarized M1-like macrophages secreted chemokines (CCL5 and CCL3), which facilitated T lymphocyte infiltration into the tumor bed." (PMID 41029711, 2025). "Chemokines such as CCL2, CCL5, and CXCL12 are known to recruit myeloid‐derived suppressor cells (MDSCs) to the tumor microenvironment, where they suppress T‐cell responses and promote tumor growth." (PMID 40145607, 2025). "Chemokines such as CXCL4, CXCL9, CXCL10, CXCL11, CXCL13, and CCL5 contribute to the accumulation of CD8+ T cells and B lymphocytes in tumor tissues and inhibit angiogenesis." (PMID 41223031, 2025).
tumor (continued). "Studies have shown that CAFs upregulate levels of C-C motif chemokine ligands such as CCL2, CCL5, and CCL20 to coordinate activation of HCC cell ERK/PKM2 and TGF-β pathways to enhance tumor metastasis phenotype and regulate tumor metabolism." (PMID 40028341, 2025). "Blocking CCL5 signaling significantly inhibits ENH‐induced TAMs recruitment, neovascularization, and tumor growth." (PMID 40536254, 2025). "The IFNβ downstream chemokines CCL5 and CXCL10 are important for the recruitment of immune cells into the tumor microenvironment, driving the antitumor immune response." (PMID 39700406, 2025). "Studies demonstrate that activation of the Axin2-Snail axis increases CCL5 expression, which subsequently modulates CAF function and influences other stromal components, ultimately promoting tumor invasion and metastasis." (PMID 41445742, 2025). "In mouse melanoma tumours, NK cells promote cDC1 anti‐tumour functions by enhancing their accumulation in the TME via production of cDC1 chemoattractants CCL5 and XCL1 and cDC growth factor Flt3L." (PMID 40878038, 2025). "Tumor microenvironment (TME) soluble mediator (Ccl2, Ccl3, Ccl4, Ccl5) and tumor cell marker (NeuN, Gpr17) RNA expression was quantitated by qRT-PCR." (PMID 41497446, 2025). "In a study using an in vitro model with AGS cells to investigate the modulation of the CCL5/CCR5 axis, it was found that receptor expression increased with rising chemokine levels in the tumor microenvironment." (PMID 39827154, 2025). "While the −SG diet induces tumor cell secretion of chemokines such as CCL5 and CXCL11 to promote CD8+ T cell recruitment, it concurrently increases tumor lactate production, which stabilizes PD-L1 via lactylation." (PMID 41303712, 2025). "These cytokines, including CCL5 and CXCL10, up‐regulate tumour cell lysis via large amounts of granzyme B.40, 41Collectively, the activation of the classical pathway results in immunosuppression against tumours." (PMID 41275427, 2025). "Subsequently, to further demonstrate the effect of CCL5 in vivo, we subcutaneous injected MC38 cells transfected with siCcl5 to conduct a subcutaneous tumor model." (PMID 39773173, 2025). "However, studies have also suggested that CCL4/CCL5/CCR5 may play some role in anti‐tumor therapy." (PMID 40145607, 2025). "We concluded that ENH upregulates CCL5, leading to an accumulation of TAMs in LUAD, which ultimately promotes tumor angiogenesis and growth." (PMID 40536254, 2025). "By binding CCR5, CCL5—secreted by tumor or stromal cells—guides the migration of CD8 + T cells to sites of inflammation and tumor tissue." (PMID 41444923, 2025). "CCL5 also shapes an immunosuppressive TME by polarising monocytes and myeloid cells into tumour-promoting phenotypes, leading to effector T-cell exhaustion." (PMID 40361472, 2025). "For instance, increased CCL5 expression by activated endothelial cells during lung metastasis resulted in monocyte recruitment, while CCR5 antagonist treatment reduced tumor cell survival and inhibited metastasis." (PMID 39566333, 2025). "In breast cancer, cancer cells induce the recruitment and accumulation of MDSCs at the tumor site by secreting factors such as S100A9, CCL5, and so on." (PMID 41219968, 2025). "CAR-NK cells also prime the tumour site by secreting chemokines such as CCL3, CCL5, and IL-8, which recruit CAR-T cells and improve their infiltration into the TME." (PMID 40624498, 2025). "Tumor‐derived PGE2 can impair NK cell function by negatively affecting the release of XCL1 and CCL5 and the expression of their receptors on cDC1." (PMID 39973474, 2025). "As previously acknowledged, CCL5 and CXCL10 serve as crucial signaling bridges between NK cells, T cells, and tumor cells." (PMID 40678068, 2025). "CCL5 is involved in the recruitment of immune cells such as CD8+ T cells, CD4+ T cells, and M1 macrophages, enhancing anti-tumor immunity." (PMID 40777006, 2025).